PGR (progesterone receptor)
Diseases named in the same sentence as PGR in open-access papers (continued):
Sharing a sentence is not in itself a finding about the gene and the disease.
tumor (continued). "Our study indicated that macropinocytosis enhanced by PGR down-regulated the availability of glucose and lipids in tumor cells, and this inhibition was able to resume when suppressing macropinocytosis by EIPA." (PMID 38424455, 2024). "In a fourth RNA-Seq data set consisting of 73 samples, expression of ESR1 and PGR was again significantly increased in tumor samples following ADT." (PMID 38625747, 2024). "According to the ASCO/CAP guideline update, 2019: Samples with 1% to 100% of tumor nuclei positive for ER or progesterone receptor (PgR) are interpreted as positive." (PMID 39129012, 2024). "To evaluate the effect of Abi + Prog on NK cell-mediated tumor killing efficacy, we first assessed the impact of PgR overexpression, which is required by Prog to initiate the genomic pathway, in a co-culture system of NK-92 and U87MG-luc cells." (PMID 39103871, 2024). "Hormone receptor status, such asestrogen receptor (ER) and progesterone receptor (PR) expression, can providevaluable information about the hormone dependency of the tumor." (PMID 39224544, 2024). "The tumor shows positive staining for ER and progesterone receptor (PR), which play a role in tumor evolution, especially in childbearing age." (PMID 39803071, 2024). "The inhibition of estrogen and progesterone receptor expression by Bay provides a significant beneficial effect of this drug for tumor growth, making them less responsive to the mitogenic effect of these ovarian steroids." (PMID 38994944, 2024). "Next, we analyzed the number of kataegis events in ERpHER2n tumors stratified by PAM50 subtype (restricted to Luminal A versus Luminal B subtypes due to sample sizes), progesterone receptor (PR) status, tumor grade, lymph node status, and HRDetect status." (PMID 38658600, 2024). "The immunohistochemical (IHC) profile of the tumor indicated estrogen receptor (ER) expression at 95%, progesterone receptor (PR) expression at 98%, a Ki67 index of 30%, and a HER2/neu score of +3." (PMID 39766180, 2024). "Tumors with progesterone receptor expression exhibited significantly lower levels of SEMA3A expression in the tumor cells (p = 0.0097)." (PMID 38263416, 2024). "Among the tumor biomarkers, we paid close attention to the proteins that are clinically relevant to breast cancer, such as estrogen receptor (ER), progesterone receptor (PR), and HER2." (PMID 38413598, 2024). "Tumor subtypes were defined by expression of estrogen receptor (ER), progesterone receptor (PR), and human epidermal growth factor receptor 2 (HER2) based on immunohistochemistry." (PMID 38916820, 2024). "Firstly, assessment of tumour progesterone receptor (PGR) mRNA levels, a well-known ER-regulated gene, showed that PGR mRNA decreased in a dose-dependent manner across the entire dosing range." (PMID 38740899, 2024). "To further validate the effect of PGR in mediating tumor growth in vivo, we developed a mice xenograft tumor model, implanting Capan-1 cells expressing control or shRNAs targeting PGR." (PMID 38424455, 2024). "IHC analysis for 113 BC specimens demonstrated that 58.4% and 54.9% of the tumours were ER and PgR positive, respectively." (PMID 39256703, 2024). "Chemo-hormonal therapies are increasingly used to combat disease progression and prolong therapeutic efficacy in patients with tumor biopsies showing cells with estrogen receptor (ER), progesterone receptor (PR), and human EGF receptor 2 (HER2) positivity." (PMID 39409987, 2024). "When considering tumor characteristics, no influence on margin status was found regarding age, tumor size, tumor weight, histological type, menopausal status, estrogen and progesterone receptor status, and Ki67 status." (PMID 39606532, 2024). "Histological examination assessed tumor type, grade, receptor structure (ER, PgR, HER2), Ki67 index, and lymph node involvement." (PMID 39518625, 2024).
tumor (continued). "The survival of BC patients is influenced by clinical factors such as tumor stage, tumor grade, estrogen receptor (ER) and progesterone receptor (PR) status, as well as human epidermal growth factor receptor 2 (HER2) status." (PMID 39104479, 2024). "Subtypes of BC are classified by the expression of tumor markers: estrogen receptor (ER), progesterone receptor (PR), and HER2 status." (PMID 39194688, 2024). "Altogether, these data demonstrate that the upregulation of PGR in PDAC promotes macropinocytosis to support tumor growth." (PMID 38424455, 2024). "Estrogen receptor status, progesterone receptor status, age and tumor stage are another important predictive prognostic features." (PMID 39145224, 2024). "In detail, the molecular subtyping of BC relies on the examination of crucial tumor markers through immunohistochemistry tests, such as estrogen receptor(ER), progesterone receptor (PR), HER2, Ki-67 and etc.." (PMID 37957623, 2023). "Several tumor characteristics such as nuclear grade, estrogen receptor alpha, progesterone receptor, triple-negative phenotype, Cyclin D1 immunohistochemistry, and Mucin 1 differed significantly between the created groups." (PMID 36769215, 2023). "Hormone receptor-positive (HR +) breast cancer, with tumor expression of the estrogen receptor (ER) and/or progesterone receptor (PR), is the most common form of the disease." (PMID 36401732, 2023). "Immunohistochemistry (IHC) stains for somatostain receptor 2a (SSTR2a) and progesterone receptor (PR) were positive in the tumor cells." (PMID 38066633, 2023). "BCs present themselves as a heterogeneous tumor family, usually categorized by their hormone receptor status for estrogen receptor (ER), progesterone receptor (PR) and human epidermal growth factor receptor 2 (HER2)." (PMID 37760571, 2023). "Correlations of tumor clinicopathological characteristics with ERα, ERβ, PGR, and AR protein expression in malignant colonic tissues from all patients (n = 120) by Pearson’s correlation test." (PMID 37206439, 2023). "For those models with available patient tumour sections, the corresponding PDXs and PDXOs samples were assessed for oestrogen receptor (ER) and progesterone receptor (PR) expression." (PMID 38062117, 2023). "Among the piRNAs, the expression level of hsa_piR_004307 was significantly and inversely correlated with the PGR protein level in the tumor tissue." (PMID 37569592, 2023). "In our study, tumor grade 3, estrogen receptor negativity, progesterone receptor negativity, HER2 strong positivity (score 3+), and the use of neoadjuvant trastuzumab were associated with higher pathological complete response rates." (PMID 37871573, 2023). "Pathological examination of the tumor biopsy specimen at the time led to the diagnosis of papillary carcinoma, which was positive for estrogen receptor (ER) and progesterone receptor (PR)." (PMID 37384235, 2023). "Meanwhile, immunohistochemical staining of the tumor cells was positive for αSMA, ER, and PgR, and slightly positive for h-caldesmon, CD43, and CD99." (PMID 36765343, 2023). "In ER and PgR-positive BC, estrogens induce the proliferation of tumor cells and support the progression of the disease." (PMID 37111307, 2023). "Tumor histology, age at time of diagnosis and progesterone receptor status were prognostic factors for US." (PMID 35780401, 2023). "The available clinical features of our study included tumor stage, tumor size, tumor subtype, Ki67 levels, estrogen receptor (ER) status, progesterone receptor (PR) status and human epidermal growth factor receptor 2 (HER2) status." (PMID 37274256, 2023). "The patients’ characteristics (age, tumor size, PgR status, nuclear grade, clinical and pathological responses to NET, and number of axillary lymph node metastases) were well balanced between the two groups." (PMID 36947277, 2023).
tumor (continued). "Herein, we measured ERα, ERβ, PGR, and AR protein expression in archived paired malignant and non-malignant colonic tissues, and the results were analyzed based on gender, age, and tumor sidedness." (PMID 37206439, 2023). "Treatment selection in advanced breast cancer is based on a patient’s and disease characteristics, including, among others, tumor burden, previous treatments, and tumor phenotype, in particular estrogen and progesterone receptor expression and HER2 status." (PMID 37878202, 2023). "A marginal residual hazard to opposite direction was seen also for PgR status, tumor size, and the number of affected lymph nodes, suggesting an overall poor fit of the PREDICT ER-positive score for the BRCA2 carriers from CIMBA." (PMID 37173335, 2023). "We then integrated Xenium and Visium data to derive differentially expressed genes from a tumor region containing cells expressing RNA of three receptors (ERBB2 + /ESR1 + /PGR+)." (PMID 38114474, 2023). "There are many prognostic factors for MuBC; lymph node involvement (N) is the most significant factor, followed by the age at diagnosis, tumor size (T), progesterone receptor (PR) status, and nuclear grade." (PMID 37817207, 2023). "This tumor is nearly always estrogen (ER) and progesterone receptor (PR)-positive, and mostly human epidermal growth factor receptor type 2 (HER2)-negative." (PMID 37365622, 2023). "This tumor is characterized by the low expression of progesterone receptor, estrogen receptor, and human epidermal growth factor receptor 2, thus making TNBC resistant to receptor- and HER-based molecular targeted therapy." (PMID 37841433, 2023). "For instance, luminal cells with low ESR1/PGR/HER2 were enriched in the tumor zone, and luminal B cells (L5) were enriched in the interface zone." (PMID 37644609, 2023). "In this study, tumor histology, age at time of diagnosis and progesterone receptor status are significant prognostic markers in univariate analysis." (PMID 35780401, 2023). "Correlations of tumor clinicopathological characteristics with ERα, ERβ, PGR, and AR protein expression in malignant colonic tissues from male (n = 64) and female (n = 56) patients by Pearson’s correlation test." (PMID 37206439, 2023). "The maximum diameter of the clinical tumor extension at the initial treatment was 0.8 cm (ER-positive, PgR-positive, HER2-negative, nuclear grade 2)." (PMID 38054154, 2023). "Further analysis revealed a significant correlation between XBP1 splicing rate and various clinicopathological features of patients, including positive progesterone receptor status and larger tumor size (p < 0.05)." (PMID 37706018, 2023). "There is a significant association between BMI and age at diagnosis, family history, progesterone receptor, receptor status, bilaterality, and tumour stage." (PMID 36576677, 2023). "Additional explorative post-hoc subgroup analyses were performed in patients with tumours expressing both the oestrogen and progesterone receptor." (PMID 36992863, 2023). "Accordingly, we analyzed the correlation of the RNA transcript levels between ER-α encoding gene ESR1, PR encoding gene PGR, and HER2 encoding gene ERBB2 in tumor samples of BC patients." (PMID 36902278, 2023). "Changed HER2 status in distant metastases correlated with lower proliferation rates and higher ER expression in primary tumours, and among metastases of hormone receptor-positive (HR+) tumours—with weak progesterone receptor (PR) expression in primary tumours." (PMID 37120672, 2023). "The main pathological findings were a residual tumor diameter measuring 53 mm, a number of residual lymph node metastases found in four of 18 nodes, ER and PgR positivity, HER2 negativity, and a histological response to preoperative therapy of grade 1a." (PMID 37361653, 2023).
tumor (continued). "The AJCC guidelines recommend anatomic staging based on tumor size, and the existence of lymphadenopathy and distant metastases, histological tumor grade, and expression of ER, progesterone receptor (PR), HER2, and Ki-6716." (PMID 37380659, 2023). "Last, we tested clinical factors (pathologic stage, grade, tumor size (pT), node status (pN), luminal subtype A vs B, progesterone receptor (PR) status, ERBB2 status, Ki‐67 status, and invasive ductal adenocarcinomas vs others, menopause status)." (PMID 37491786, 2023). "Assessed parameters were tumor grade, proliferation index, estrogen receptor, progesterone receptor, HER2 status, type of neoadjuvant therapy, pathologic complete response rates, and overall survival." (PMID 37871573, 2023). "At the time of first diagnosis of ABC (newly diagnoses or relapsed), a tumor biopsy is necessary to determine estrogen receptor (ER), progesterone receptor (PR), and human epidermal growth factor receptor 2 (HER2) status [I, A]." (PMID 37148499, 2023). "In this study, our objective was to explore the relationship between tumor progesterone receptor levels and RNA profiles (miRNAs, piwiRNAs, and mRNAs) to understand their biological characteristics and behavior." (PMID 37569592, 2023). "Compared to IDC patients, ILCs present with larger tumor sizes, more frequent lymph node invasion and higher probabilities of estrogen receptor (ER) and progesterone receptor (PR) positivity." (PMID 37064116, 2023). "This clinical nomogram incorporates patient age, tumor size, progesterone receptor (PR) status, tumor grade, and histologic subtype." (PMID 37059742, 2023). "Estrogen receptor (ER)/progesterone receptor (ER) positive tumours have been shown to have lower proliferation and thus lower grade." (PMID 37396100, 2023). "TNBC is characterized by the absence of HER-2 (Human epidermal growth factor receptor-2), progesterone receptor (PR), or estrogen receptor (ER) expression on tumor cells." (PMID 37064114, 2023). "It is a heterogeneous disease, characterized by the primary tumor status of the estrogen receptor (ER), progesterone receptor (PR) and epidermal growth factor receptor 2 (HER2)." (PMID 37189370, 2023). "The relationships between them and the expressions of ER, PgR, and AR of tumor tissues, evaluated immunohistochemically, were analyzed." (PMID 36721218, 2023). "Adjuvant therapy in raloxifene, tamoxifen, or GnRH agonists like leuprolide acetate and goserelin have proven beneficial where the tumor is estrogen and progesterone receptor sensitive." (PMID 35177124, 2022). "Most ER+ tumours are also Progesterone Receptor (PR) positive, and this kind of tumour is usually less aggressive." (PMID 36289735, 2022). "A multivariate analysis was performed in which age at primary surgery, pathological tumor classification, tumor grade, progesterone receptor and HER2 status were included." (PMID 35151276, 2022). "Adjuvant therapy is chosen according to clinical characteristics (lymph node status, tumor size, and tumor grade), patient physiologic status and age, and IHC status in three tumor receptors: estrogen receptor (ER), progesterone receptor, and HER2." (PMID 36923306, 2022). "In the training and validation groups, NI had no statistical correlation with patient age, multicentric/multifocal tumors, tumor type, histologic grade, estrogen receptor expression, progesterone receptor expression, or Ki-67 status." (PMID 36034380, 2022). "EBV infection was correlated with the tumor size, menopausal status, axillary lymph node metastasis, vascular invasion, Ki-67 index, clinical stage, and estrogen and progesterone receptor expressions (all P < 0.05)." (PMID 35842661, 2022). "Multiple subtypes of breast cancer (BCa) exist with tumours clinically stratified by the presence of oestrogen receptor (ER), progesterone receptor (PR) and HER2 proteins." (PMID 35884550, 2022).
tumor (continued). "PCR was achieved in 9 of 14 (64%; 95% CI: 39–89%) tumours which were ER-positive, and PgR-negative compared to 6 of 19 (32%; 95% CI: 11–52.5%) which were ER-positive, PgR-positive (p=0.11)." (PMID 35833190, 2022). "Compared with tumours that positively express oestrogen receptor, progesterone receptor, and human epidermal growth factor receptor 2, TNBC is more aggressive and has worse treatment effects and prognosis." (PMID 35690609, 2022). "Progesterone receptor (PR) staining was positive in 30% of tumor cells, which was a lower percentage of tumor cells compared with ER (a); Ki-67 proliferative index was positive in 20-30% (magnification ×100; (b))." (PMID 35784659, 2022). "The predominant clinical presentation of tumor phenotypes was estrogen receptor (ER)-positive, progesterone receptor (PR)-positive, and HER2-negative (77.7%); further, 10.2% of the tumors were triple-positive, and 1.2% were triple-negative." (PMID 35805063, 2022). "In a multivariable analysis, the test for interaction between chemotherapy and RS was statistically significant (p = 0.023) when controlling for patient age, tumour size, ER and progesterone receptor (PR) status, and tumour grade." (PMID 35448187, 2022). "The primary tumor histological feature was estrogen receptor (ER)(−)/progesterone receptor (PR)(−)/human epidermal growth factor receptor (HER-2)(+) in 21 patients (77.8%)." (PMID 36064544, 2022). "Differences in tumor histology, grade and stage at diagnosis were also observed, as well as in the status of the estrogen receptor, the progesterone receptor and HER2." (PMID 36581893, 2022). "Eleven cases had sufficient number of metastatic tumor cells for further analysis, and the expression patterns of ER, PgR, and HER2 in the metastatic tumor cells reflected the pathology assessment of the corresponding primary tumors." (PMID 34165864, 2022). "From a clinical perspective, a diagnosis of Br-NET, despite the term tumor, implies an identical treatment to any BC of comparable grade, stage, and hormonal profile, being most Br-NETs estrogen (ER) and progesterone (PgR) receptor positive." (PMID 36243799, 2022). "In patients with bilateral tumours, 1 had bilateral HER2 positive, ER positive and PgR-positive tumours while the other had 1 HER2 positive, ER positive and PgR positive and the other triple negative." (PMID 35833190, 2022). "This is arguably a result of their tumor characteristics based on immunohistochemistry properties [estrogen receptor (ER), progesterone receptor (PR), human epidermal growth receptor-2 (HER-2), and Ki-67 proliferation index]." (PMID 36338611, 2022). "ER and PgR expression is evaluated using immunohistochemistry and is reported as the percentage of positive tumor nuclei." (PMID 35454806, 2022). "More precisely, expression levels of both ER and PgR, tumor grading, and overexpression of the human epidermal growth factor receptor 2 (HER2) reached levels of agreement equal to 55%, 58%, and 64%, respectively (items 1.d, 1.e, and 1.f)." (PMID 36387212, 2022). "Histologically, the tumor shared some characteristics with metanephric stromal tumor, and the tumor cells were estrogen and progesterone receptor-positive." (PMID 36699622, 2022). "Since the tumor cells lack the receptors ER, PgR and HER2, common treatments such as endocrine therapy and anti-HER2 therapy are ineffective." (PMID 35566456, 2022). "Biomarkers of interest included estrogen receptor (ER; specifically, the alpha variant), progesterone receptor (PgR), Ki67, HER2, and tumor molecular subtype." (PMID 36010992, 2022). "A series of reports indicated that factors associated with prognosis included tumor size, number of lymph node metastases, tumor type, tumor stage, histological grade, estrogen receptor and progesterone receptor status, chemotherapy, and antiestrogens." (PMID 36197680, 2022). "A descriptive subgroup analysis involving PgR− and PgR+ tumor patients in (A) revealed similar results in PFS24 (33.3% vs 32.1%)." (PMID 37435469, 2022).